NOD1 (nucleotide binding oligomerization domain containing 1)
Diseases named in the same sentence as NOD1 in open-access papers (continued):
Sharing a sentence is not in itself a finding about the gene and the disease.
diabetes (continued). "Nucleotide-binding oligomerization domain-containing protein 1 (NOD1) participates in multiple pathological processes, including tumor development and septic shock, and plays important roles in the pathogenesis of diabetes in adipose, liver and cardiac tissues." (PMID 29760746, 2018). "A selective inhibitor of NOD1 protected against PGN-induced autonomic neuropathy and therefore promotes bone marrow HSPC rejuvenation in diabetes." (PMID 35966130, 2022). "Intriguingly, we found that NOD1 depletion in hematopoietic cells does not exert any influence on diabetes-induced alterations in TNFα and IL10, underscoring the intricate nature of the inflammatory response operating within the diabetic retina." (PMID 38336763, 2024). "As anticipated, circulating NOD1 activity was higher in patients with diabetes without microvascular complications than in healthy controls." (PMID 38336763, 2024). "Although genetic variants in NOD1 and NOD2 have not been identified in genome wide association studies (GWAS) of diabetes or other metabolic syndromes, this may not be surprising due to the strong influence that environmental factors have in disease development." (PMID 33503814, 2021).
periodontitis (10 papers, 2014 to 2025). An acute or chronic inflammatory process that affects the tissues that surround and support the teeth. "The importance of NOD1 stimulation has been suggested because stimulation of NOD1 induces alveolar bone loss and periodontitis." (PMID 34071605, 2021). "Current studies regarding the role of NOD1 in periodontitis bone loss remain ambiguous." (PMID 36043447, 2022). "Nucleotide oligomerization domain receptor 1 (NOD1) is substantially expressed in periodontium of individuals with chronic periodontitis." (PMID 36043447, 2022). "The high expression of NOD1 in chronic periodontitis was confirmed in our study, and NOD1 activation by DAP reduced the osteogenic potential of hPDLSCs." (PMID 36043447, 2022). "Porphyromonas gingivalis induces intracellular adhesion molecule production which is correlated to the severity of periodontitis and this process can be mediated by NOD1 in periodontal fibroblasts." (PMID 36043447, 2022). "In this study, we detect considerably elevated levels of NOD1 expression in periodontal tissues in periodontitis." (PMID 36043447, 2022). "Immunohistochemistry (IHC) staining and Immunofluorescence (IF) staining were carried out to confirm the presence and distribution of NOD1 in periodontitis." (PMID 36043447, 2022). "We observed that NOD1 is substantially expressed in periodontal tissue in individuals with chronic periodontitis." (PMID 36043447, 2022). "IE‐DAP from PGN structure is an important PAMP recognized by NOD1, its synthesis is significantly increased in periodontitis patients' subgingival plaque." (PMID 36043447, 2022). "In our study, we tested the NOD1 protein level and the intensity of IHC and IF in periodontal tissues collected from healthy people and patients with periodontitis." (PMID 36043447, 2022). "Our findings indicate a novel role of NOD1 in microbe‐affected osteogenesis in periodontitis and present a possible target for clinical treatment." (PMID 36043447, 2022). "NI1060 induces periodontitis by stimulation of Nod1, an innate immune receptor that recognizes small peptidoglycan-like molecules containing D-γ-glutamyl-meso-diaminopimelic acid (iE-DAP) derived from bacteria." (PMID 27409077, 2016). "Like Aggregatibacter actinomycetemcomitans (Aa), a bacterium that is associated with the development of aggressive periodontitis in humans, it releases high amounts of unidentified iE-DAP-containing molecules that stimulate Nod1." (PMID 27409077, 2016). "Our study revealed the expression status of NOD1 in periodontitis." (PMID 36043447, 2022). "The elevated NOD1 expression suggests NOD1 might be an important receptor for the recognition of periodontal pathogens in periodontitis." (PMID 36043447, 2022). "Therefore, this study focused on the activation status of NOD1 in periodontitis and its effect on the osteogenic capacity of human periodontal ligament stem cells (hPDLSCs) as well as the underlying mechanism." (PMID 36043447, 2022). "It is controversial whether NOD1/NOD2 plays a pro-inflammatory or anti-inflammatory role in periodontitis." (PMID 36569059, 2022). "Moreover, proteins were extracted from two groups of periodontal tissues, and subsequent Western blot detected significantly higher NOD1 expression in patients with chronic periodontitis." (PMID 36043447, 2022). "A recent study indicated that NOD1 is critical for commensal-induced periodontitis." (PMID 25503380, 2014). "NOD1 and NOD2 are two types of NLRs and are involved in the recognition of periodontal pathogens and the process of periodontitis." (PMID 36569059, 2022). "NOD1, a representative PRR from the NLRs family, has been reported to interfere with periodontitis by triggering immune responses." (PMID 36043447, 2022).
periodontitis (continued). "However, BMVs produced by other periodontal pathogens, Tannerella forsythia and Treponema denticola, induced a weak or no NOD1/2 response respectively, highlighting the different abilities of BMVs to activate NOD1 and NOD2 in the context of periodontitis." (PMID 35967403, 2022). "Histological staining and Western blot were utilized to assess NOD1 expression in the periodontium of people with or without periodontitis." (PMID 36043447, 2022). "Additionally, NOD1 and NOD2 in the NLRC family may also participate in inflammation in periodontitis." (PMID 34177950, 2021).
Sepsis (10 papers, 2012 to 2023). Sepsis is defined as life-threatening organ dysfunction caused by a dysregulated host response to infection. "In this study, we did not detect different levels of circulating IL-6 or neutrophil accumulation in the lungs during sepsis in Nod1-, Nod2-, Nod1/Nod2- and Rip2-deficient mice compared to WT septic mice." (PMID 25084278, 2014). "We have proceeded to show that stimulation of NOD1 in human endothelial cells induces multiple chemokine and cytokine response genes that are implicated in sepsis including CXCL6, CXCL8, IL1-β and TNFα." (PMID 22870324, 2012). "Accordingly, the expression of genes involved in the innate immune response, including NOD1, changes in critically ill patients suffering sepsis and related malnutrition." (PMID 34066406, 2021). "Severe COVID-19, ALI/ARDS and sepsis patients are all characterized by the activation and increased expression of TLR2, TLR4 and NOD2 (and sometimes NOD1, as well) and their associated synergisms (which are quite numerous)." (PMID 33672738, 2021). "Similar levels of MPO activity were observed in the lungs of WT, Nod1/Nod2- and Rip2-deficient mice 24 h after CLP-induced severe sepsis, further confirming that these pathogen sensors are not relevant to neutrophil sequestration in the lung." (PMID 25084278, 2014). "This study aimed to evaluate the role of the NLR family members Nod1 and Nod2 in the chemokines production and neutrophil recruitment to the infectious site in polymicrobial sepsis." (PMID 25084278, 2014). "Neutrophil recruitment into the peritoneal cavity was assessed in Nod1- and Nod2-deficient mice following CLP-induced sepsis." (PMID 25084278, 2014). "Here, we evaluated the role of Nod1, Nod2 and MyD88-dependent signaling in the chemokine production and neutrophil recruitment to the infectious site during sepsis induced by cecal ligation and puncture (CLP) in C57Bl/6 mice." (PMID 25084278, 2014). "NFκB is a central pro-inflammatory transcription factor in the aetiology of sepsis therefore our findings add weight to the concept of the NOD1 signalling pathway as a potential target in the development of new therapies." (PMID 22870324, 2012). "Moreover, in sepsis- and ischemia-induced acute kidney disease models, NOD1/2 DKO mice were demonstrated to be protected against renal disease." (PMID 29609537, 2018). "The local levels of IL-6 and TNF-α were also similar in WT, Nod1- and Nod2-deficient mice 24 h after severe sepsis induction (data not shown)." (PMID 25084278, 2014). "We also evaluated whether Nod1 or Nod2 is involved in the sequestration of neutrophils in the lung, thus contributing to pulmonary dysfunction during sepsis." (PMID 25084278, 2014). "Unexpectedly, neutrophil recruitment was similar in WT, Nod1- and Nod2-deficient mice 6 and 12 h after non-severe sepsis induced by CLP (data not shown)." (PMID 25084278, 2014). "In agreement with the results of the neutrophil recruitment assay, the bacterial loads in the peritoneal cavity and the blood were also similar in WT, Nod1- and Nod2-deficient mice 6 h after non-severe and 6, 12 or 24 h after severe sepsis induced by CLP." (PMID 25084278, 2014). "Taking this information into consideration, we evaluated whether Nod1 or Nod2 is involved in the recruitment of neutrophils to the site of infection during polymicrobial sepsis." (PMID 25084278, 2014). "To evaluate whether Nod1 or Nod2 mRNAs were systemically expressed by leukocytes during severe sepsis, we isolated peripheral blood mononuclear cells (PBMCs) and neutrophils from naïve and septic mice 6 h after CLP." (PMID 25084278, 2014). "In addition, we demonstrated that plasma-derived IL-6 levels in Nod1- and Nod2-deficient or WT mice were similar 6, 12 or 24 h after severe sepsis, as well as 6 h after non-severe sepsis induction." (PMID 25084278, 2014).
Sepsis (continued). "Because both Nod1 and Nod2 sense bacterial cell wall components and signal via Rip2 kinase, we investigated whether there was a possible synergy between Nod1 and Nod2 during severe polymicrobial sepsis." (PMID 25084278, 2014). "To confirm that the absence of a phenotype in Nod1- and Nod2-deficient mice during polymicrobial sepsis was not the consequence of a microbiotic variation in the knockout mice, we inoculated the cecal bacteria isolated from WT mice into the peritoneal cavities of WT, Nod1- and Nod2-deficient mice." (PMID 25084278, 2014). "Compared with wild-type (WT) mice, mice lacking NOD1 are more likely to be infected with early pneumococcal septicemia, which implies that NOD1 plays a key role in initiating innate defense and promoting a rapid response to infection." (PMID 36920176, 2023). "Based on our findings, we cannot exclude the roles of Nod1 and Nod2 in sepsis in the absence of major signaling pathways induced by TLR." (PMID 25084278, 2014). "By contrast, the whole bacteria observed during CLP-induced sepsis do not activate Nod1 and Nod2, or does it in a weak intensity." (PMID 25084278, 2014). "In this work, we demonstrate that in our experimental conditions, differences in the microbiota of WT and Nod1-, Nod2- or Rip2-deficient mice are not responsible for the absence of a phenotype in CLP-induced sepsis." (PMID 25084278, 2014). "Here we did not evaluate the role of Nod1 or Nod2 on the eicosanoid and complement production and we cannot explain the apparent discrepancy regarding the involvement of Nod2 in sepsis." (PMID 25084278, 2014). "Altogether, these data suggest that TLRs, but not Nod1 and Nod2, play a major role in the resolution of sepsis due to the establishment of the local response in polymicrobial sepsis." (PMID 25084278, 2014). "Based on that, we would be tempted to suggest that Nod1 and Nod2 do not play a major role in polymicrobial sepsis, since the absence of them did not alter the survival." (PMID 25084278, 2014). "In agreement with the previous data, WT, Nod1- and Nod2-deficient mice showed similar survival rates in CLP-induced non-severe, moderate and severe sepsis." (PMID 25084278, 2014). "In conclusion, our data indicate that Nod1 and Nod2 do not play a major role in the resolution of polymicrobial sepsis in our experimental conditions." (PMID 25084278, 2014). "It is beyond the scope of this study to speculate as to how NOD1 and TLR4 mediated inflammation might proceed throughout the blood vessel over longer periods of sepsis." (PMID 22870324, 2012). "This provides the opportunity to dissect the relative roles of NOD1 and TLR4 in more complex models of sepsis and may lead to new therapeutic approaches in septic shock and related microvascular pathologies including acute lung injury." (PMID 22870324, 2012). "Because we showed that Nod1/Nod2 signaling was not indispensable for the production of chemokines and neutrophil recruitment to the infection site during polymicrobial sepsis, we investigated the importance of MyD88, the main adaptor protein of the TLR family, in these events." (PMID 25084278, 2014). "Importantly, no alteration was observed in the Nod1 or Nod2 expression levels 6 h after polymicrobial sepsis induction." (PMID 25084278, 2014). "Based on the known roles of Nod1 and Nod2, members of the NLR family, in the induction of an immune response during infection, we investigated whether these receptors were involved in the physiopathology of sepsis." (PMID 25084278, 2014). "We demonstrated that, under our experimental conditions, neither Nod1 nor Nod2 was essential to the onset of inflammation at the infection site, analyzed by chemokine production and neutrophil recruitment, during polymicrobial sepsis." (PMID 25084278, 2014). "This set of results indicates that neither Nod1 nor Nod2 is involved in the release of neutrophil chemotactic mediators and, consequently, in the recruitment of neutrophils during CLP-induced sepsis." (PMID 25084278, 2014).
Sepsis (continued). "Collectively, these data indicate that an additive response of Nod1 and Nod2 is not essential in neutrophil recruitment or bacterial control during CLP-induced severe sepsis." (PMID 25084278, 2014). "In this context, it is unusual that the expression of Nod1 and Nod2 was not altered after CLP-induced sepsis." (PMID 25084278, 2014). "Taken together, these results suggest that Nod1 and Nod2 do not play a role in survival, chemokine production, neutrophil recruitment to the infectious site, or sequestration to the lungs after CLP-induced severe sepsis." (PMID 25084278, 2014). "Altogether, these data show that Nod1, Nod2 and Rip2 are not required for local chemokine production and neutrophil recruitment during CLP-induced sepsis, and they reinforce the importance of MyD88-dependent signaling for initiation of a protective host response." (PMID 25084278, 2014).
type 2 diabetes (10 papers, 2014 to 2026). "NOD1 mRNA expression is elevated in the subcutaneous adipose tissue of obese mice and humans with metabolic syndrome, and NOD1 is elevated in immune cells from individuals with type 2 diabetes." (PMID 40616268, 2025). "More recently, further evidence has demonstrated that NOD1 and NOD2 are also linked to several inflammatory diseases in addition to CD, including Type 2 Diabetes (T2D), and asthma." (PMID 35967403, 2022). "However there is compelling evidence that deregulated NOD1/2 signaling is associated with inflammation-associated diseases such as early-onset sarcoidosis, uveitis, neuropathic pain, rheumatoid arthritis or solid cancers and more recently with allergic asthma and type 2 diabetes mellitus (T2DM)." (PMID 31632962, 2019). "Additionally, there is a significant increase in NOD1 expression in the myocardium of individuals diagnosed with type 2 diabetes mellitus." (PMID 39906040, 2024). "In line with the wider tissue distribution of NOD1 compared to most other PRRs including NOD2, recent evidence indicates roles for NOD1 in diverse disorders including type 2 diabetes associated adipose tissue inflammation and in pathogen-induced inflammation in vascular endothelium." (PMID 24806487, 2014).
glioma (9 papers, 2019 to 2025). A benign or malignant brain and spinal cord tumor that arises from glial cells (astrocytes, oligodendrocytes, ependymal cells). "Bioinformatics analysis using data from the CGGA database showed that the expression of NOD1 in glioma was associated with several clinical features, particularly tumor grading." (PMID 41363048, 2025). "Compared with the Glioma group, the expressions of NOD1, RIP2, Iba1, IL‐1β, and CD206 in the Glioma + ML130 group were all decreased." (PMID 41363048, 2025). "This study highlighted the essential role of NOD1 in glioma progression and its positive correlation with WHO grades." (PMID 41363048, 2025). "In vitro experiments were conducted to examine NOD1 and RIP2 expression in glioma cells treated with ML130, an NOD1 inhibitor, to investigate how the NOD1/RIP2 pathway affects glioma progression." (PMID 41363048, 2025). "According to WB analysis, NOD1 expression was significantly lower in non‐tumor tissues and significantly higher in high‐grade gliomas than that in low‐grade gliomas (p < 0.05)." (PMID 41363048, 2025). "Treatment with ML130 inhibited glioma cell proliferation, migration, and invasion while reducing NOD1 and RIP2 expression." (PMID 41363048, 2025). "Correlation analysis demonstrated that NOD1 expression correlated positively with glioma grade and negatively with rADC values." (PMID 41363048, 2025). "We explored the mechanism of NOD1/RIP2 in glioma progression through bioinformatics analysis, clinical sample evaluation, and in vivo and in vitro experiments." (PMID 41363048, 2025). "The expression of RIP2 in ML130‐treated glioma cells was explored to elucidate the effect of NOD1 on the downstream signaling molecule RIP2." (PMID 41363048, 2025). "NOD1 expression was considerably higher in human glioma tissues and positively correlated with glioma malignancy." (PMID 41363048, 2025). "An in situ glioma model was established to confirm the impact of the NOD1/RIP2 pathway on microglial polarization in vivo." (PMID 41363048, 2025). "High NOD1 expression was associated with several clinical features, particularly World Health Organization (WHO) grades and glioma survival times." (PMID 41363048, 2025). "It facilitates glioma progression by promoting microglial M2 polarization through the NOD1/RIP2 pathway." (PMID 41363048, 2025). "Targeting the NOD1/RIP2 pathway effectively inhibits glioma progression, offering a theoretical basis for precise and individualized glioma treatment." (PMID 41363048, 2025). "This study confirmed that the NOD1/RIP2 pathway accelerated glioma progression by promoting microglial M2 polarization." (PMID 41363048, 2025). "IHC analysis revealed more NOD1‐positive cells in glioma tissues than in non‐tumor tissues, with high‐grade gliomas having a markedly greater proportion of NOD1‐positive cells than low‐grade gliomas (p < 0.01)." (PMID 41363048, 2025). "Bioinformatics analysis showed that NOD1 was highly expressed in glioma tissues and strongly correlated with glioma grade." (PMID 41363048, 2025). "It facilitates glioma progression by promoting microglial M2 polarization via the NOD1/RIP2 pathway." (PMID 41363048, 2025). "ML130‐treated glioma‐bearing rats exhibited reduced tumor growth, suppressed NOD1/RIP2 pathway activation, and inhibited microglial M2 polarization." (PMID 41363048, 2025). "The rADC value was negatively correlated with NOD1 expression in the brain tissues of patients with glioma, providing an imaging biomarker for predicting the NOD1 expression." (PMID 41363048, 2025). "The scratch and transwell assays showed that active NOD1 in FDX1-silenced glioma cells increased invasion and migration ability." (PMID 37301546, 2023). "The human glioma tissues were pathologically stained to detect the expression of the NOD1 protein." (PMID 41363048, 2025). "Bioinformatics analysis was conducted to assess NOD1 expression in glioma tissues." (PMID 41363048, 2025).